ESRRG (estrogen related receptor gamma)
Diseases named in the same sentence as ESRRG in open-access papers (continued):
Sharing a sentence is not in itself a finding about the gene and the disease.
IntraUterine Growth Restriction (2 papers, 2019). "Here we investigated maternal E2 levels and placental CYP19A1 and ESRRG expressions in pregnancies with IntraUterine Growth Restriction (IUGR)." (PMID 31069202, 2019).
lung carcinoma (2 papers, 2022). "Both mRNA and protein expression of ESRRG can be induced by short-term BPA exposure in lung cancer cell lines, breast cancer cell lines, adipocytes, hepatocytes, and zebrafish." (PMID 35220427, 2022). "However, our results are similar to previous studies in breast and lung cancer cell lines, which reported that both ESRRG mRNA and protein expression could be increased by short-term BPA exposure." (PMID 35220427, 2022).
neuroblastoma (2 papers, 2018 to 2022). Neuroblastoma (NB) is the most common solid, extracranial childhood tumor. "Orphan nuclear receptor estrogen-related receptor gamma (ERR-gamma) induces GSK3β phosphorylation by upregulating PLK2 responsible for the differentiation of neuroblastoma SH-SY5Y cells." (PMID 29497051, 2018).
Rb (2 papers, 2022 to 2024). "In clinical observations, heightened expression of ESRRG has been noted in human retinoblastoma tumor cells that infiltrate the optic nerve, a phenomenon strongly correlated with metastatic potential and dismal prognosis." (PMID 38672640, 2024). "ESRRG as an essential mediator of hypoxic adaptation and cell survival in retinoblastoma offers a promising therapeutic target." (PMID 35984874, 2022).
rectal cancer (2 papers, 2012 to 2014). A primary or metastatic malignant neoplasm that affects the rectum. "Copy number increase of EFNA1 (1q22), PTGS2 (1q31.1), KDM5B (1q32.1), ESRRG (1q41), KIFC1 (6p21.32), PBX2 (6p21.32) and SOX4 (6p22.3) were only detected in rectal cancer in array CGH." (PMID 23158542, 2012). "Notably, many of these genes (ADRA1A, BARHL2, ERAS, ESRRG, RNF220 and ST6GALNAC5) are also targets of the Polycomb Repressor Complex-2, further supporting an important role of epigenetic crosstalk in controlling rectal cancer therapeutic responsiveness." (PMID 25261372, 2014).
Renal cyst (2 papers, 2023 to 2024). A fluid filled sac in the kidney. "Concordantly, the genes encoding PPARα and estrogen-related receptors (PPARGC1A, PPARA, ESRRA and ESRRG) were all downregulated in renal cysts." (PMID 39000280, 2024).
autoimmune disease (1 paper, 2023). A disorder resulting from loss of function or tissue destruction of an organ or multiple organs, arising from humoral or cellular immune responses of the individual to their own tissue constituents. "Mice deficient in estrogen-related receptor gamma gene (Esrrg) spontaneously develop autoimmune diseases in association with dysfunctional Treg cells and mitochondrial defects." (PMID 37098006, 2023).
cholangiocarcinoma (1 paper, 2025). A carcinoma that arises from the intrahepatic biliary tree (intrahepatic cholangiocarcinoma) or from the junction, or adjacent to the junction, of the right and left hepatic ducts (hilar cholangiocarcinoma). "In our prior pan-cancer analysis, we hypothesized that ESRRG had a positive association with lymph node metastasis in cholangiocarcinoma (CHOL)." (PMID 40356747, 2025).
Cholecystitis (1 paper, 2025). The presence of inflammatory changes in the gallbladder. "Our study revealed that 58% (29/50) of GBC samples exhibited positive ESRRG expression, significantly higher than the positive rate (24%, 12/50) observed in cholecystitis samples." (PMID 40356747, 2025). "Moreover, compared to cholecystitis, the expression level of ESRRG in GBC was much greater." (PMID 40356747, 2025).
cleft lip (1 paper, 2018). Congenital defect in the upper lip where the maxillary prominence fails to merge with the merged medial nasal prominences. "Our in silico analyses revealed an intricate network of genes linking cleft lip, ESRRG and two vitamins in particular: vitamins A and D. These GxE effects are novel and warrant further investigations to unravel the potential interplay between vitamins and ESRRG variants." (PMID 29535761, 2018). "Our in silico analyses using Hetionet revealed that the cleft lip phenotype is influenced by vitamins A and D through a network of genes connected to ESRRG." (PMID 29535761, 2018).
dysplastic (1 paper, 2018). "Indeed, ESRRG expression was found to be significantly suppressed in the Gan mice in gastric hyperplasia and decreased further in dysplastic tumors." (PMID 29765046, 2018).
gastritis (1 paper, 2018). Inflammation of the stomach. "To determine whether ESRRG expression is lost during gastric oncogenesis, we took advantage of the Gan-mouse model system where an initially induced gastritis sometimes progresses to malignant GC15." (PMID 29765046, 2018).
head and neck cancer (1 paper, 2022). A primary or metastatic malignant neoplasm affecting the head and neck. "Methylation of ESRRG and CCNA has been investigated in head and neck cancers and is associated with poor prognosis." (PMID 35794182, 2022).
leukemia (1 paper, 2022). A malignant (clonal) hematologic disorder, involving hematopoietic stem cells and characterized by the presence of primitive or atypical myeloid or lymphoid cells in the bone marrow and the blood. "Therefore, the mutation of the ESRRG gene found in our study may be involved in the occurrence and development of leukemia as an important driving factor." (PMID 36612032, 2022).
lupus (1 paper, 2021). "Overall, we found a similar association between low ESRRG expression in T cells and lupus susceptibility in mice and humans, and our results suggest that ESRRG may contribute to human T cell metabolism." (PMID 34156979, 2021). "We found that the expression of human ESRRG, which is high in Tregs, was lower in CD4+ T cells from patients with lupus than in healthy controls." (PMID 34156979, 2021).
lymph node metastasis (1 paper, 2025). "High ESRRG expression in GBC was significantly associated with advanced TNM stage, deeper invasion, and lymph node metastasis." (PMID 40356747, 2025).
meningioma (1 paper, 2022). A generally slow growing tumor attached to the dura mater. "When considering mitotic activity in meningiomas, we found negative correlations with DNAm for ARHGDIA and DOK7 and positive correlations for ESRRG and OTX1 (both correlating with all proliferation indices)." (PMID 36551712, 2022).
Multiple Myeloma (1 paper, 2025). "This study identifies Estrogen-Related Receptor Gamma (ERRγ) as a clinically relevant oncogene in multiple myeloma (MM), with its elevated expression associated with advanced disease stages and osteolytic bone damage." (PMID 40918468, 2025).
orofacial cleft (1 paper, 2018). A disorder of facial skeleton that is characterized by cleft lip and/or cleft palate that result in feeding, speech and hearing problems caused by failures during development. "The impact of specific variants in ESRRG on the risk of orofacial clefts is also uncharted territory, but several lines of evidence point to a biologically plausible link between estrogens, ESRRG and craniofacial malformations." (PMID 29535761, 2018). "The connection between vitamins and variants in ESRRG is novel in the context of orofacial clefts." (PMID 29535761, 2018).
sexual precocity (1 paper, 2018). "The ESRRG (Estrogen-Related Receptor Gamma) gene was associated with sexual precocity in Nellore heifers." (PMID 29293544, 2018). "It should be noted that the ESRRG and XKR4 genes can also influence lipid metabolism demonstrating the importance of these genes for sexual precocity in Nellore heifers since genes that affect fat deposition and, consequently, body condition play an important role in Zebu breeding." (PMID 29293544, 2018).
tumor (50 papers, 2013 to 2026). "In THYM, ESRRG is associated with increased infiltration of immunosuppressive cells, such as M2 macrophages and regulatory T cells, facilitating tumor progression." (PMID 40356747, 2025). "In this study, the finding that ESRRG expression was higher in SCLC tumors than in the control group and that this higher expression was associated with increased overall survival suggested that ESRRG has the potential to act as a tumor suppressor in SCLC." (PMID 37958393, 2023). "Next, we conducted an analysis to examine the potential associations between the IHC score of ESRRG and the level of tumor cell differentiation in a sample of 94 patients with ESCC." (PMID 37679788, 2023). "ESRRG encodes a member of nuclear receptor superfamily of transcription factors and has been shown to be a tumor suppressor in different types of cancer." (PMID 34660292, 2021). "Higher expression of NR0B1 and IL20RA were associated with higher tumor histologic grade, and lower expression of ESRRG were associated with higher tumor histologic grade." (PMID 34868990, 2021). "To confirm the regulation of SF3B1R625H on ESRRG, we infected the adenovirus carrying SF3B1R625H mutation in primary cultured tumor cells, and the results showed that the cryptic ESRRG transcript was only observed in the Ad-SF3B1R625H group." (PMID 32427851, 2020). "Moreover, Kaplan–Meier analysis of published tumor datasets revealed that high expression of ESRRG was associated with poor prognosis in patients with SCLC." (PMID 39085398, 2024). "In the case of lactotroph tumor cells, abnormally spliced mRNA derived from the ESRRG gene, which encodes ERRγ, results in a mutant ERRγ protein, which has shown to have an abnormally high affinity for PIT1 and potently enhance PIT1-dependent PRL gene transcription." (PMID 35892862, 2022). "We investigated the mechanisms underlying the ESRRG-mediated suppression of tumor growth." (PMID 29765046, 2018). "Conversely, in LGG, ESRRG correlates with increased infiltration of NK cells and dendritic cells, thus promoting anti-tumor immunity." (PMID 40356747, 2025). "ESRRG plays a dual role in cancer, acting as an oncogene in some cancers while exhibiting tumor-suppressive functions in others." (PMID 40356747, 2025). "Our pan-cancer analysis reveals ERRs as critical regulators of tumor immunity and progression, with ESRRG emerging as a key oncogenic driver in GBC." (PMID 40356747, 2025). "For example, an increase in m6A modification levels can trigger the splicing of estrogen-related receptor gamma gene (ESRRG) mRNA, resulting in the upregulation of estrogen-related receptor gamma (ERRγ) expression in BC drug-resistant tumor cells." (PMID 38711100, 2024). "In an in vivo assay using a xenograft mouse model, the promotion of tumor growth induced by ESRRG knockdown was partially offset by the silencing of PKM." (PMID 37679788, 2023). "To assess the tumor suppressor function of ESRRG in vivo, we subcutaneously injected the stable cell lines into nude mice and monitored tumor growth." (PMID 37679788, 2023). "Consistent with the in vitro results, ESRRG overexpression suppressed tumor growth in nude mice compared to the control group." (PMID 37679788, 2023). "Univariate Cox analysis incorporating ESRRG expression, age, gender, pathological stage, and tumor grade revealed that ESRRG is an independent predictive marker for the prognosis of ESCC (HR = 0.064, 95% CI 0.012−0.335, P < 0.01)." (PMID 37679788, 2023). "In this study, we have observed that the overexpression of ESRRG or the administration of DY131 has the potential to significantly inhibit lactate production in tumor cells." (PMID 37679788, 2023). "The results showed that 92.5% of tumor tissues exhibited decreased mRNA levels of ESRRG compared to paracancerous tissues, while only 7.5% of tumor tissues showed increased ESRRG expression." (PMID 37679788, 2023).
tumor (continued). "Human estrogen receptor-related receptor gamma (ERRγ) was reported to suppress cell proliferation and tumor growth of androgen-sensitive and androgen-insensitive PC cells and JICD overexpression resulted in a depletion of ERRγ (ESRRG)." (PMID 36428807, 2022). "Recently, a GWAS analysis of somatotroph tumor cells showed aberrant splicing of various mRNAs, including that of the estrogen-related receptor γ (ERRγ) gene (ESRRG)." (PMID 35892862, 2022). "For example, as a negative regulator of Wnt signaling pathway, ESRRG plays a tumor suppressor role in GC." (PMID 34840985, 2021). "Molecular studies revealed that Sophoridine depends on Estrogen-related receptor gamma (ESRRG) to perform tumor-suppressive activities and which promotes the degradation of β-catenin, but not ubiquitin-proteasome pathway." (PMID 32571331, 2020). "Patients with a higher ESRRG level had good clinical outcomes and vice versa across multiple sample sets, consistent with a tumor suppressor role of ESRRG in GC." (PMID 29765046, 2018). "In our current study, we identified estrogen-related receptor gamma (ESRRG; also known as ERRγ) as a potential tumor suppressor in GC by genomic analysis." (PMID 29765046, 2018). "In summary, we have demonstrated that ESRRG is a novel tumor suppressor that inhibits Wnt signaling in GC." (PMID 29765046, 2018). "Consistent with the decreases observed in tumor growth, we observed reduced cell proliferation, as assessed by Ki67 expression, upon ESRRG overexpression." (PMID 29765046, 2018). "Our in vitro and in vivo experiments thus collectively demonstrated that ESRRG plays a tumor suppressive role in GC." (PMID 29765046, 2018). "Our data thus suggest that ESRRG negatively regulates Wnt signaling components and that this contributes to its tumor suppressive properties." (PMID 29765046, 2018). "Consistently, inhibition of tumor growth by ESRRG overexpression in a xenograft mouse model was rescued by the re-introduction of TCF4/LEF1, and Ki67 expression was also rescued." (PMID 29765046, 2018). "To identify potential molecular targets, we analyze gene expression data from GC patients and identify the nuclear receptor ESRRG as a candidate tumor suppressor." (PMID 29765046, 2018). "We have identified a novel tumor-suppressive role for ESRRG in GC that is mediated via the antagonism of Wnt signaling." (PMID 29765046, 2018). "The activated networks (HIF1A, ESRRA, ESRRG) had many proteins that were increased in tumor tissues that overlapped between the three targets, such as ENO1/ENO2, ALDOA, and LDHA." (PMID 27128972, 2016). "Immunofluorescence analysis of tumor tissues showed that regions with high ESRRG expression had elevated PD-L1 level and decreased CD8+ lymphocyte infiltration, while regions with low ESRRG expression had decreased PD-L1 level and upregulated CD8+ lymphocyte infiltration." (PMID 40356747, 2025). "Targeting ESRRG could enhance immunotherapies by modulating the tumor immune microenvironment, reducing immune checkpoint expression, and restoring anti-tumor immunity." (PMID 40356747, 2025). "We hypothesized that the inhibition of ESCC cell growth by ESRRG is closely related to its regulation of tumor cell metabolic reprogramming." (PMID 37679788, 2023). "ESRRG may act as a tumor suppressor in GC, and the higher its expression, the better the prognosis and survival of patients." (PMID 37653798, 2023). "To investigate whether the inhibition of glycolysis activity and tumor growth by ESRRG is mediated through PKM, we performed knockdown of PKM in ECa109 and KYSE510 cells." (PMID 37679788, 2023). "In contrast, the knockdown of ESRRG significantly enhanced xenograft tumor growth." (PMID 37679788, 2023).
tumor (continued). "Rb cells demonstrate constitutive ESRRG expression that is enriched in oxygen-poor regions beyond ~100 μm from tumor blood vessels and in vitreous seeds, which consist of clusters of Rb cells that proliferate in the hypoxic vitreous cavity and portend chemoresistance and poor outcome in Rb." (PMID 35984874, 2022). "In addition, tumor volume and weight were also significantly decreased in ESRRG-overexpressing NCI-N87 cells." (PMID 29765046, 2018). "In addition, genomic profiling analysis revealed that, similar to other tumor suppressor genes in GC, ESRRG suppresses the Wnt signaling pathway." (PMID 29765046, 2018). "When genes were ranked according to fold changes between GC and normal gastric samples, ESRRG was one of top-ranked TFs and NRs, exhibiting a greater than 10-fold downregulation in cancer tissues (normal vs. tumor: -14.851 fold in GSE29272; -16.514 fold in GSE26899; -23.608 fold in GSE13861)." (PMID 29765046, 2018). "Thus, the decreased levels of ESRRG in GC are likely to be through a mechanism that is distinct from conventional tumor suppressive TFs." (PMID 29765046, 2018). "To investigate whether ESRRG functions as a tumor suppressor, we examined whether it affects cancer cell growth." (PMID 29765046, 2018). "We next evaluated whether the tumor suppressive properties of ESRRG were due to the suppression of Wnt signaling." (PMID 29765046, 2018). "As expected, ESRRG suppressed tumor growth in this in vivo mouse model." (PMID 29765046, 2018). "Together, these findings suggest that RB1 dampens the hypoxia-induced surge in ESRRG activity and that loss of RB1 abolishes this homeostatic mechanism, resulting in nascent Rb cells becoming increasingly dependent on ESRRG in the hypoxic tumor microenvironment." (PMID 35984874, 2022). "Immunohistochemical staining and Western blot analysis of xenograft tumor tissues from previous nude mice experiments yielded similar results, with ESRRG overexpression decreasing PKM2 expression and ESRRG knockdown increasing PKM2 expression." (PMID 37679788, 2023). "Similar with results from TCGA-KIRC and GSE126964, the expression of ALDOB, ESRRG, and EFHD1 were much lower in tumor cells than that in other intrinsic renal cells." (PMID 34660292, 2021). "On the other hand, miR-107-5p and miR-222-3p targeting ERa and miR-205 targeting Estrogen Related Receptor Gamma (ESRRG) act as oncomiRNAs by enhancing migration, invasion in vitro or/and tumor growth in vivo." (PMID 34298609, 2021). "ESRRG is a member of the estrogen receptor-related receptor (ESRR) family, which has been identified as a tumor suppressor gene in several cancers." (PMID 32426279, 2020). "In these types of cancer, miR-378 seemed to be an oncogene, and enhanced tumor cell survival, promoted tumor growth and metastasis in some tumors via regulation of the target genes SuFu, Fus-1, HMOX1, ESRRG and GABPA." (PMID 24555885, 2014). "The results demonstrated that knockdown of ESRRG downregulated PCNA, MMP-2, VIMENTIN, and N-cadherin, while upregulating E-cadherin expression, suggesting that ESRRG may promote tumor migration and invasion by modulating EMT." (PMID 40356747, 2025). "Among the cell types, ESRRG was predominantly expressed in epithelial cells, suggesting that ESRRG exerts its regulatory functions largely through tumor cells rather than through immune cells and stromal cells." (PMID 39085398, 2024). "Given the significant correlation between elevated ESRRG expression and SCLC metastasis, we investigated whether ERRγ controls SCLC cell invasion and tumor metastasis." (PMID 39085398, 2024). "We observed a significant increase in PKM2 mRNA levels in tumor tissues, which exhibited a negative correlation with ESRRG expression." (PMID 37679788, 2023). "Additionally, tumor volume and weight were remarkably decreased in ESRRG overexpression ESCC cells, while ESRRG knockdown ESCC cells increased tumor volume and weight compared to the control group." (PMID 37679788, 2023).